USP30 (ubiquitin specific peptidase 30)
Description:
Deubiquitinating enzyme tethered to the mitochondrial outer membrane that acts as a key inhibitor of mitophagy by counteracting the action of parkin (PRKN): hydrolyzes ubiquitin attached by parkin on target proteins, such as RHOT1/MIRO1 and TOMM20, thereby blocking parkin's ability to drive mitophagy. Preferentially cleaves 'Lys-6'- and 'Lys-11'-linked polyubiquitin chains, 2 types of linkage that participate in mitophagic signaling. Does not cleave efficiently polyubiquitin phosphorylated at 'Ser-65'. Acts as a negative regulator of mitochondrial fusion by mediating deubiquitination of MFN1 and MFN2 (By similarity).
Synonyms: MGC10702; FLJ40511
Tractability: Small molecule: a structure with a bound ligand is known; a high-quality ligand is known. Antibody: UniProt predicts a signal peptide or a membrane-spanning region. PROTAC: UniProt records ubiquitination sites on it; ubiquitination databases record sites on it; its protein half-life has been measured; a small molecule that binds it is known.
Target class: Enzyme; Hydrolase
Chemical probes: USP30inh (high quality)
Gene: Protein-coding gene on chromosome 12 (109,023,089 to 109,088,023, forward strand). Ensembl gene ENSG00000135093.
Subcellular location: Mitochondrion outer membrane
Pathways (Reactome):
Autophagy: Pexophagy
Metabolism of proteins: Ub-specific processing proteases
Gene Ontology:
Molecular function: cysteine-type deubiquitinase activity; cysteine-type endopeptidase activity; protein binding; deubiquitinase activity
Biological process: negative regulation of mitophagy; protein deubiquitination; protein K11-linked deubiquitination; protein K6-linked deubiquitination; mitochondrial fusion; pexophagy
Cellular component: mitochondrial outer membrane; mitochondrion; peroxisomal membrane
Genetic constraint (gnomAD): Loss-of-function variants: 35 observed, 61.34 expected, observed/expected ratio (o/e) 0.57, 90% interval 0.44 to 0.76. The upper end of that interval is the gene's LOEUF score, 0.76, which puts it in group 3 of 6, group 1 being the genes least tolerant of losing a copy. Missense variants: 506 observed, 636.61 expected, observed/expected ratio (o/e) 0.79, 90% interval 0.74 to 0.86. Synonymous variants: 225 observed, 252.49 expected, observed/expected ratio (o/e) 0.89, 90% interval 0.8 to 1.
Homologues: Orthologues: chimpanzee USP30 (100% identical), macaque USP30 (99% identical), dog USP30 (93% identical), guinea pig USP30 (93% identical), mouse Usp30 (90% identical), rat Usp30 (89% identical), pig USP30 (84% identical), tropical clawed frog usp30 (63% identical), rabbit USP30 (63% identical), zebrafish usp30 (55% identical), zebrafish USP30 (38% identical), Drosophila melanogaster Usp30 (30% identical). Paralogues in human: USP44 (24% identical), USP49 (23% identical), USP3 (21% identical), USP33 (20% identical), USP32 (20% identical), USP20 (19% identical), USP4 (19% identical), USP45 (19% identical), USP6 (19% identical), USP11 (18% identical), USP19 (18% identical), USP16 (18% identical), and 59 more.
Diseases named in the same sentence as USP30 in open-access papers:
USP30 is named in the same sentence as 44 diseases in open-access papers, as found by Europe PMC text mining. Sharing a sentence is not in itself a finding about the gene and the disease. The quoted sentences say what the papers report.
Parkinson disease (20 papers, 2015 to 2025). A progressive degenerative disorder of the central nervous system characterized by loss of dopamine producing neurons in the substantia nigra and the presence of Lewy bodies in the substantia nigra and locus coeruleus. "MTX115325, a CNS-penetrant USP30 inhibitor with oral bioavailability, prevented dopaminergic neuron loss in α-synuclein Parkinson’s disease models, underscoring its therapeutic promise." (PMID 40918504, 2025). "Interest in the therapeutic potential of USP30 inhibitors has been driven by their application in Parkinson disease, for which some patients have loss of function mutations in the PRKN gene." (PMID 34844982, 2022). "Dysregulation of USP30 can lead to retention and accumulation of dysfunctional mitochondria, a hallmark of Parkinson’s disease." (PMID 34391779, 2021). "The Usp30 protein also appears to be associated with the development of Parkinson’s symptoms." (PMID 30837828, 2019). "Research has shown that inhibiting USP30 can enhance mitophagy, reducing oxidative stress and improving the health of neurons, especially in models of Parkinson’s disease." (PMID 40918504, 2025). "In summary, inhibiting USP30, enhancing mitophagy, clearing damaged mitochondria, and protecting dopaminergic neurons constitute a promising disease-modifying strategy for Parkinson’s disease." (PMID 40918504, 2025). "This establishes USP30 inhibition as a promising strategy for combinatorial cancer therapies beyond its established role in Parkinson’s disease." (PMID 40918504, 2025). "Other deubiquitinating enzymes such as USP30 and USP35 have been implicated in Parkinson’s disease through their roles in regulating mitophagy." (PMID 38017009, 2023). "Dampening functional levels of the mitochondrial deubiquitylating enzyme Ubiquitin-specific protease 30 (USP30) has been suggested as an effective therapeutic strategy against neurodegenerative disorders such as Parkinson’s Disease." (PMID 37385347, 2023). "We have a particular interest in a mitochondria-localised deubiquitylase (DUB), USP30, which is an actionable target for Parkinson’s disease." (PMID 37100444, 2023). "USP30 inhibition confers neuroprotection in Parkinson's disease through rescuing the defective parkin-mediated mitophagy, promoting mitochondrial degradation and maintenance the integrity of mitochondria." (PMID 33609088, 2021). "USP30 inhibition is beneficial for Parkinson's disease through promoting mitochondrial clearance to ensure a healthy mitochondrial network." (PMID 33609088, 2021). "A new inhibitor of the deubiquitylase USP30, an actionable target relevant to Parkinson’s Disease, is introduced and characterised for parameters related to mitophagy." (PMID 32636217, 2020). "It will be of interest to elucidate if S3 can also abolish the USP30-dependent downregulation of mitophagy in Parkinson’s disease." (PMID 26445063, 2015). "Whether enhanced mitochondrial quality control through inhibition of USP30 can protect dopaminergic neurons is currently being explored in a clinical trial for Parkinson’s disease." (PMID 40325251, 2025). "In dopaminergic neurons derived from Parkinson’s disease patients with Parkin RBR E3 ubiquitin protein ligase (PRKN) loss-of-function mutations, the benzosulphonamide compound 39 effectively restored mitophagy to near-normal levels by inhibiting USP30." (PMID 40918504, 2025). "USP30 has been proposed to regulate mitophagy, a relevant Parkinson’s disease mechanism." (PMID 37957154, 2023). "Thus, inhibition of USP30 represents an actionable target to correct pathologies associated with PINK1 or PRKN defects, such as Parkinson disease or pulmonary fibrosis." (PMID 34844982, 2022). "Accordingly, inhibition of USP30 represents a potential actionable drug target for intervening the pathologies associated with PINK1/Parkin deficiency-induced mitophagy dysfunction, such as Parkinson’s disease and pulmonary fibrosis." (PMID 35308234, 2022).
Parkinson disease (continued). "USP30 is supposed to be a promising therapeutic target for Parkinson's disease." (PMID 33609088, 2021). "USP30, a deubiquitinase that targets mitochondrial proteins, may present another promising target to facilitate mitophagy, since improved mitochondrial function was obtained upon USP30 depletion in different Parkinson’s disease models." (PMID 32373609, 2020). "Therefore, the inhibition of USP30 is assumed to be potentially beneficial for Parkinson's disease by promoting mitochondrial clearance and quality control." (PMID 26445063, 2015). "In neurodegenerative diseases, the development of brain-penetrant USP30 inhibitors with good drug-like properties may slow down or reverse the progression of diseases like Parkinson’s disease by enhancing mitophagy and improving mitochondrial function, leading to significant breakthroughs." (PMID 40918504, 2025). "In the context of Parkinson’s disease treatment, inhibiting USP30 increases translocase of outer mitochondrial membrane 20 (TOM20) ubiquitination and promotes mitophagy, offering a potential therapeutic strategy for Parkinson’s disease caused by PTEN-induced kinase 1 (PINK1) or Parkin mutations." (PMID 40918504, 2025). "Identified as a USP30 trigger for Parkin-dependent amplification leading to autophagy death in Parkinsons disease, FT3967385 selectively acts on USP30." (PMID 38960968, 2024). "Here, the authors show that Usp30 knockout mice and USP30 inhibitors like MTX115325 demonstrate neuroprotective responses in an alpha-synuclein mouse model of Parkinson’s disease." (PMID 37957154, 2023). "For these reasons, both USP30 and CYLD are currently targets for therapeutic development to treat Parkinson’s disease and cancer." (PMID 34391779, 2021).
hepatocellular carcinoma (8 papers, 2022 to 2025). A malignant tumor that arises from hepatocytes. "USP30 is highly expressed in both hepatocellular carcinoma and oral squamous cell carcinoma and is associated with poor prognosis, but the role of USP30 in breast cancer was previously unclear." (PMID 38146008, 2024). "USP30 is a deubiquitinase that has been previously reported to promote tumour progression and lipid synthesis in hepatocellular carcinoma." (PMID 38146008, 2024). "USP30 has been reported to promote lipid accumulation and tumour progression by stabilising ACLY in hepatocellular carcinoma, and the recruitment of USP30 stabilises DRP1 to promote hepatocarcinogenesis." (PMID 38146008, 2024). "In this review, we will summarize the molecular structure, and regulation of USP30, and the latest discoveries about USP30 in human diseases, such as hepatocellular carcinoma, pulmonary fibrosis, and neurodegenerative diseases." (PMID 35308234, 2022). "Firstly, USP30 was phosphorylated in human hepatocellular carcinoma (HCC)." (PMID 35308234, 2022). "Its pathophysiological significance extends to cancer, where dysregulation of USP30 promotes hepatocellular carcinoma (HCC) through the IKKβ‐USP30‐ACLY lipogenesis axis and drives breast cancer progression via Snail stabilization." (PMID 41306556, 2025). "The mitochondrial deubiquitination enzyme USP30 plays an important role in hepatocellular carcinoma (HCC) driven by high fat diets (HFDs)." (PMID 35392171, 2022). "IKKβ phosphorylates and stabilizes USP30, promoting USP30-mediated deubiquitination of ACLY and FASN induction, leading to the occurrence of hepatocellular carcinoma." (PMID 39944823, 2025). "The interaction between USP30 and ACLY leads to the deubiquitination of ACLY, resulting in the increased stability of ACLY, and thereby promoting adipogenesis, inflammation and tumorigenesis in hepatocellular carcinoma." (PMID 38426936, 2024). "In hepatocellular carcinoma (HCC) models (Hep3B and HepG2 cells), inhibition of either GNPAT or USP30 significantly reduces DRP1 protein levels, triggering mitochondrial fusion and suppressing cancer cell proliferation and HCC progression." (PMID 40918504, 2025). "In addition, USP30 deubiquitinates and stabilizes ACLY and FASN and is overexpressed in the high-fat diet (HFD)-induced hepatocellular carcinoma (HCC)." (PMID 37176148, 2023).
breast carcinoma (5 papers, 2022 to 2025). "Our study showed that USP30 is highly expressed in breast cancer and is associated with poor prognosis in breast cancer." (PMID 38146008, 2024). "USP30 has also been implicated in breast cancer progression by stabilizing Snail." (PMID 41306556, 2025). "The results demonstrated that USP30 transcripts are significantly reduced in breast cancer tissues compared to normal breast tissue, with basal‐like (primarily triple‐negative) specimens showing the most pronounced downregulation among all molecular subtypes." (PMID 41306556, 2025). "Our study unveils a novel tumor‐suppressive mechanism of nuclear USP30 in breast cancer cells through mitochondrial retrograding signaling." (PMID 41306556, 2025). "To evaluate the clinical significance of USP30 in breast cancer, we performed a comprehensive analysis of TCGA, GEO, and METABRIC datasets." (PMID 41306556, 2025). "In our study, we demonstrated the binding of USP30 and Snail in breast cancer cells for the first time and showed that USP30 inhibits k48 ubiquitination degradation of Snail and thus positively regulates Snail." (PMID 38146008, 2024). "In our study, we found that USP30 promotes the progression of breast cancer, which is consistent with previous studies." (PMID 38146008, 2024). "Deletion of Snail eliminated these effects, which indicates that USP30 regulates the progression of breast cancer via EMT." (PMID 38146008, 2024). "To further demonstrate the role of USP30 in breast cancer, we overexpressed USP30 in MCF-7 and MDA-MB-231 cells using plasmids, and we knocked down USP30 using siRNA." (PMID 38146008, 2024). "In summary, we investigated the role and mechanism of USP30 and Snail in breast cancer progression, deubiquitination-related processes and chemotherapy sensitivity." (PMID 38146008, 2024). "All our results suggest that PTX-induced apoptosis was partially mediated by USP30/Snail axis in breast cancer." (PMID 38146008, 2024). "In our study, we identified the role of USP30 in breast cancer and explored its mechanism of action." (PMID 38146008, 2024). "We compared USP30 mRNA expression levels between breast cancer and normal cohorts by using Gene Ontology (GO) analyses and examined using the R “clusterProfiler” tool, the results showed higher USP30 mRNA expression in the tumour group." (PMID 38146008, 2024). "Invasion and migration assays were also performed and showed that USP30 overexpression enhanced the prometastatic phenotype in breast cancer cell lines." (PMID 38146008, 2024). "In view of the in vitro results, we then established an in vivo xenograft model to validate the role of USP30 in breast cancer growth and metastasis." (PMID 38146008, 2024). "To verify the clinical relevance of USP30 to breast cancer, we examined USP30 expression in 100 breast cancer tissues and 10 normal breast tissues." (PMID 38146008, 2024). "Our results suggest that USP30 promotes the proliferation, invasion and migration of breast cancer cells." (PMID 38146008, 2024). "Subsequently, our mechanistic experiments verified that USP30 regulates breast cancer progression and EMT by binding to Snail and deubiquitinating Snail." (PMID 38146008, 2024). "In conclusion, we identified Snail as a specific substrate of USP30 and showed that USP30 stabilises Snail via its deubiquitinase activity, which promotes breast cancer metastasis and chemosensitivity." (PMID 38146008, 2024). "Bioconductivity analysis showed that USP30 protein expression levels were high in breast cancers of different molecular stages." (PMID 38146008, 2024). "DUB3 promotes breast cancer metastasis by deubiquitinating Snail; thus, we further explored the mechanism by which USP30 regulates Snail." (PMID 38146008, 2024). "We investigated the effect of USP30 on the sensitivity of breast cancer chemotherapy because USP30’s effect on breast cancer treatment." (PMID 38146008, 2024).
breast carcinoma (continued). "In our study, we found that USP30 was highly expressed in breast cancer samples and correlated with a poor patient prognosis." (PMID 38146008, 2024). "Considering the established function of nuclear USP30 in inhibiting WNT signaling and cancer stemness characteristics, we hypothesized that enhancing nuclear USP30 expression could impede breast cancer metastasis." (PMID 41306556, 2025). "Functionally, USP30 inhibits the proliferation, migration, and invasion of breast cancer cells." (PMID 40918504, 2025). "We examined the subcellular distribution of USP30 in multiple breast cancer cell lines." (PMID 41306556, 2025). "Targeting the dynamic relocalization of USP30 from mitochondria to the nucleus may offer novel therapeutic strategies for combating breast cancer metastasis." (PMID 41306556, 2025). "Notably, comprehensive gene expression and breast cancer tissue microarray analyses reveal that USP30 is significantly downregulated in TNBC and CSCs, with reduced nuclear localization in tumors, suggesting clinical relevance." (PMID 41306556, 2025). "In this study, we validated for the first time that USP30 plays a role in breast cancer, demonstrated that USP30 could combine with and deubiquitinates Snail and extensively investigated the role of USP30 in vivo and in vitro." (PMID 38146008, 2024). "In addition, CCK-8 assays and Transwell stromal gel assays were performed to confirm the function of USP30 in breast cancer." (PMID 38146008, 2024). "In our study, we found that knockdown of USP30 decreased the viability and suppressed the proliferation and migration of breast cancer cells; conversely, overexpression of USP30 increased the viability and promoted the proliferation and migration of breast cancer cells." (PMID 38146008, 2024). "In addition, we explored the specific mechanisms of USP30 in breast cancer progression and EMT progression." (PMID 38146008, 2024). "Our study also demonstrated that USP30 diminishes the chemosensitivity of PTX in breast cancer, which suggests that USP30 may be a potential target in breast cancer." (PMID 38146008, 2024). "However, knowledge of the physiological function of USP30 in breast cancer is limited." (PMID 38146008, 2024). "Thus, our findings suggest that USP30 plays a crucial role in triggering EMT in breast cancer." (PMID 38146008, 2024). "In human osteosarcoma (U2-OS) and breast cancer (MCF7) models, USP30 depletion enhances cancer cell sensitivity to pro-apoptotic BH3 mimetics, revealing its anti-apoptotic role." (PMID 40918504, 2025). "In vitro experiments demonstrate that USP30 knockdown suppresses breast cancer cell proliferation and epithelial-mesenchymal transition (EMT), while USP30 overexpression exacerbates these processes." (PMID 40918504, 2025). "Genetic correlation analysis revealed significant positive correlations between USP30 expression and ESR1 (estrogen receptor alpha) and PGR (progesterone receptor) levels in breast cancer samples." (PMID 41306556, 2025). "USP30 promotes EMT and chemoresistance in breast cancer by stabilizing Snail protein through deubiquitination, which reduces sensitivity to paclitaxel." (PMID 40918504, 2025). "A series of experimental validations have shown that USP30 can interact with TOMM40, and USP30 deubiquitinating TOMM40 promotes the development of breast cancer." (PMID 40918504, 2025). "This clinical finding was corroborated by single‐cell RNA‐seq analysis of 32,803 high‐quality cells from 13 breast cancer datasets (E‐MTAB‐8107), where USP30 expression was restricted to a minor epithelial subpopulation." (PMID 41306556, 2025). "A CCK-8 assay showed great differences in cell viability between the USP30 knockout and control groups at 24 h, but in the Snail overexpression group, the inhibitory effect of PTX on breast cancer cell proliferation was significantly inversed." (PMID 38146008, 2024). "However, the role of USP30 in breast cancer remains unclear." (PMID 38146008, 2024).